SMAD3 (SMAD family member 3)
Diseases named in the same sentence as SMAD3 in open-access papers (continued):
Sharing a sentence is not in itself a finding about the gene and the disease.
non-small cell lung carcinoma (31 papers, 2014 to 2025). A group of at least three distinct histological types of lung cancer, including non-small cell squamous cell carcinoma, adenocarcinoma, and large cell carcinoma. "Here we examine TGF-β1/Smad3 signaling in tumor-associated neutrophils (TANs) in non-small cell lung carcinoma (NSCLC) patients." (PMID 37002229, 2023). "Here, we show that Smad3 activation in TANs is associated with a predominant N2 state of polarization and a poor outcome in patients with non-small-cell lung carcinoma (NSCLC)." (PMID 37002229, 2023). "For example, in non-small cell lung carcinoma, Smad3 has been recognized as crucial for TAN polarization, especially via TGF-β/Smad3 axis." (PMID 40387965, 2025). "For example, homoharringtonine (HT), a She-derived alkaloid, targets Smad3/TGF-β pathways in non-small cell lung cancer and synergizes with chemotherapy in leukemia treatment, as evidenced by preliminary clinical trials." (PMID 40746719, 2025). "The stability of lncRNA RMRP is enhanced through m6A modification, regulating the TGFBR1/SMAD2/SMAD3 pathway and the proliferation and progression of non-small cell lung cancer." (PMID 35585970, 2022). "In non-small-cell lung carcinoma (NSCLC), cancer metastasis was associated with inactivation of SMAD2-mediated and activation of SMAD3-mediated transcriptional programs." (PMID 32746934, 2020). "This study investigated the function of SMAD3 (SMAD family member 3) in regulating PAX6 (paired box 6) in non-small cell lung cancer." (PMID 30594196, 2018). "Moreover, nobiletin blocked TGFβ1/Smad3 signaling to inhibit EMT in human non-small-cell lung cancer." (PMID 35458126, 2022). "Moreover, TGF-β1-activated Smad3/4 complex transcriptionally upregulates N-cadherin expression in non-small cell lung cancer." (PMID 35371324, 2022). "In this study, we investigated the function of SMAD3 in non-small cell lung cancer using cell proliferation and migration experiments and explored the relationship between SMAD3 and PAX6 with double luciferase reporter experiments and chromatin immunoprecipitation assay (ChIP)." (PMID 30594196, 2018). "SMAD3 promotes the progression of non-small cell lung cancer by upregulating PAX6 expression." (PMID 30594196, 2018). "Furthermore, we show that the expression of FOSL2 correlates with activated Smad3 expression in clinical non-small cell lung cancer (NSCLC) samples." (PMID 25375657, 2014). "For example, in non-small cell lung cancer, HOXA1 promotes cell proliferation by activating the TGF-β/SMAD3 pathway." (PMID 40076953, 2025). "In non-small cell lung cancer (NSCLC), hypoxia-induced HIF-1α forms a complex with phosphorylated Smad3, which upregulates c-Myc and promotes PKM2 splicing, constructing a hypoxia-adaptive aerobic glycolysis network." (PMID 40842995, 2025). "The increased stability of LncRMRP due to m6A modification activates the SMAD2/SMAD3 pathway by enhancing TGFBR1 transcription, ultimately accelerating non-small cell lung cancer (NSCLC) progression." (PMID 36854773, 2023). "While TGFβ can increase the reduced expression of miR-143 in non-small cell lung cancer (NSCLC), the overexpression of this miRNA inhibits the endogen expression of SMAD3 at the post-transcriptional and post-translational level." (PMID 33498521, 2021). "MSI2 depletion significantly down-regulates EMT markers (TGF-β receptor 1, SMAD3, SNAI1 and SNAI2) to inhibit non-small cell lung cancer metastasis." (PMID 31952541, 2020). "To illustrate, in non-small cell lung cancer, METTL3-mediated m6A modification could enhance the stability of methylated lncRNA-RMRP transcripts, which further promotes TGFBR1 transcription and the activation of TGFBR1/SMAD2/SMAD3 signaling pathway." (PMID 40089501, 2025).
non-small cell lung carcinoma (continued). "Moreover, in non-small cell lung carcinoma (NSCLC), the activation of Smad3 in N2 TANs was negatively correlated with the N1 population and patient survival, suggesting heterogeneity in neutrophil tumor subset infiltration may impact tumor progression/regression." (PMID 38474175, 2024).
Ureteral obstruction (31 papers, 2012 to 2025). Obstruction of the flow of urine through the ureter. "On this basis, we examined the effect of BET inhibition on the phosphorylation of Smad3 and expression of Smad7 in the kidney after ureteral obstruction." (PMID 27732564, 2016). "A clear increase in phosphorylation of the SSXS motif in the Smad3 C-terminal domain was evident in the obstructed kidney and presumably plays an important role in the fibrotic response to unilateral ureteric obstruction." (PMID 24391884, 2013). "SIS3 has been shown to protect unilateral ureteral obstruction of the kidneys against fibrosis, apoptosis, and inflammation injury through the inhibition of TGF-β/Smad3 signaling." (PMID 33294466, 2020). "In other global kidney injury models (e.g., unilateral ureteral obstruction [UUO]), increased TGFβ1 production in the kidney alters the ratio of transcription factors Smad2 and Smad3, favoring activation of fibrosis programs." (PMID 32227630, 2020). "Thus,honokiol – a SIRT3 activator – counteracts kidney fibrosis inmice with unilateral ureteral obstruction.Similarly, activation of both SIRT1 and SIRT3 by resveratrolattenuates cardiac fibrosis in mice by inhibiting the TGF-β/Smad3 pathway." (PMID 38680178, 2024). "In the present study, we evaluated the role of endogenous Vasohibn‐1 VASH‐1 in regulating tubulointerstitial alterations induced by unilateral ureteral obstruction (UUO), and assessed its regulatory role on fibrogenesis and the activation of TGF‐beta/Smad3 signaling in renal fibroblasts." (PMID 24973329, 2014). "In the present study, we evaluated the role of endogenous VASH‐1 in regulating the tubulointerstitial alterations induced by unilateral ureteral obstruction (UUO), and assessed its role on fibrogenesis and the activation of Smad3 signaling in renal fibroblasts." (PMID 24973329, 2014). "In unilateral ureteric obstruction (UUO) we observed an acute (6 hr) down-regulation of nitric oxide synthase 3 (NOS3/eNOS) levels and increased phosphorylation of the linker region of Smad3 at T179 and S208 in Smad3/JNK complexes." (PMID 24391884, 2013). "Previous studies have shown that mice lacking Smad3 have reduced EMT and collagen accumulation and reduced renal tubular interstitial fibrosis after unilateral ureteral obstruction." (PMID 35628363, 2022).
heart failure (30 papers, 2013 to 2025). Inability of the heart to pump blood at an adequate rate to meet tissue metabolic requirements. "Of note, parallel studies using the same rodent heart failure model showed that activated fibroblast-specific Smad3 deletion is also associated with detrimental effects in cardiac function, highlighting the complexity of TGF-β signaling in mediating the response to cardiac stress." (PMID 36281993, 2022). "DAPA inhibits the increase in α-SMA, TGF-β, Smad2, and Smad3 levels in the myocardial tissues of aortic constriction-induced heart failure model rabbits." (PMID 41392217, 2025). "Research indicates that SMOC2 expression escalates in rats experiencing heart failure, and silencing SMOC2 can mitigate heart failure symptoms by modulating autophagy via the TGF-β1/Smad3 signaling pathway." (PMID 39717447, 2024). "Smad3 plays an essential role in heart remodelling in MI or TAC-induced heart failure models, although it plays different roles in CFs and CMs." (PMID 37840136, 2023). "First, Smad3-mediated Smad7 overexpression in infarct myofibroblasts is an important endogenous protective mechanism that reduces heart failure–related mortality and limits maladaptive ventricular fibrosis." (PMID 34905511, 2022). "Initial in vivo studies with SMAD3 global deletion demonstrated a reduction in myocardial fibrosis across several models of murine heart failure." (PMID 36281993, 2022). "It has been reported that Smad3 plays an important role in cardiac pathological processes, such as cardiac fibrosis, hypertrophy and heart failure." (PMID 30820195, 2019). "Induction of TGF-β1 by high glucose or Ang-II, which then phosphorylates and activates downstream Smad2 and Smad3 proteins, results in cardiac fibrosis, cardiac hypertrophy and heart failure; however, Smad7 can antagonize TGF-β–mediated cardiac remodeling." (PMID 23690953, 2013). "Whether PFD play its anti‐fibrotic role in heart failure via suppressing the TGF‐β1/Smad3 signalling remains unclear." (PMID 35861038, 2022). "In short, our findings suggested that epigenetic modulation of local H3K4me3 and H3K36me3 in the Smad3 promoter may be a potential therapeutic target against heart failure after MI." (PMID 31275414, 2019). "We examined whether Smad3 and Smad4 can change in this isoproterenol‐induced heart failure model." (PMID 37482908, 2023). "This activation influences key signaling pathways, including the mTOR-p70S6K, JNK, and TGF-β/Smad3, effectively reducing ISO-induced myocardial hypertrophy and fibrosis rat heart failure in vitro and in vivo models, and confirmed the targeting of 2-APQC in SIRT3 knockout mice." (PMID 38744811, 2024). "Differences in the minor allele frequencies of SMAD3 rs17228212 polymorphism between RA patients with or without CV events, Ischemic Heart Disease (IHD), Cerebrovascular Accident (CVA) or Heart Failure (HF)." (PMID 24204921, 2013).
liver cancer (30 papers, 2010 to 2025). An epithelial or non-epithelial malignant neoplasm that arises from the liver. "Taken together, the clusters demonstrate that disrupted Smad3 downstream signaling is required for loss of cytostatic TGF-β effects in liver cancer." (PMID 23991075, 2013). "To further substantiate these findings in vivo, we performed IHC staining on liver cancer specimens induced in wild‐type and Nsun5‐KO mice, which revealed a significant reduction in Smad3 content in Nsun5−/− mice, consistent with our experimental observations." (PMID 39531371, 2025). "Correlation analysis of the TCGA liver cancer database revealed a positive association between the expression levels of NAT10 and SMAD3." (PMID 41476650, 2025). "In liver cancer, YAP inhibits the nuclear translocation of Smad3, causing it to remain in the cytoplasm and inducing the generation of stem-like tumor cells." (PMID 40673277, 2025). "It is important to note that the TGF-β1/smad pathway and the roles of Smad2 and Smad3 in liver cancer are complex and multifaceted, and further research is needed to fully understand their mechanisms of action and potential therapeutic implications." (PMID 37790613, 2023). "Smad2 and Smad3 have been found to have both tumor-suppressive and tumor-promoting effects in liver cancer, depending on the context." (PMID 37790613, 2023). "Liver cancer patients with high SMAD3 expression had significantly shortened survival times in TCGA." (PMID 37790613, 2023). "The exact mechanisms by which Smad2 and Smad3 exert their effects in liver cancer are still being studied." (PMID 37790613, 2023). "SMAD2 and SMAD3 significantly positively correlated with autophagy-related scores in liver cancer patients in TCGA." (PMID 37790613, 2023). "The Cancer Genome Atlas (TCGA) database was used for comprehensively analyzing the prognostic values of SMAD2 and SMAD3 in liver cancer." (PMID 37790613, 2023). "In order to further investigate the underlying mechanism mediated the effects of ECH on the liver cancer, miRNA/ TGF-β1/Smad3 pathway was explored." (PMID 34112163, 2021). "The high expression of TGF-β1/Smad3 pathway is considered to be one of the key reasons for the occurrence of liver cancer." (PMID 34112163, 2021). "In this study, we found that LINC01234 knockdown downregulated the expression of p-Smad2, p-Smad3 in liver cancer cells and increased the level of Smad4 in Cytoplasm of Huh-7 cells." (PMID 33178601, 2020). "In HCCs, Smad3 and its phosphorylation relatives have been suggested to be the predictors of prognosis in patients with liver cancer and also serve as the biomarkers to identify patients with a high risk of recurrence." (PMID 23251252, 2013). "Notably, literature evidence underscores the critical role of SMAD3 in liver cancer progression, prompting us to focus on SMAD3 as the key downstream target of NAT10 in subsequent investigations." (PMID 41476650, 2025). "In our study, SMAD2 and SMAD3 were hazardous factors in liver cancer." (PMID 37790613, 2023). "The correlation between SMAD2, SMAD3, and autophagy-related scores in liver cancer was explored." (PMID 37790613, 2023). "SMAD2 and SMAD3 correlated with autophagy-related scores in liver cancer." (PMID 37790613, 2023). "The prognostic values of SMAD2 and SMAD3 in liver cancer were explored." (PMID 37790613, 2023). "To identify the key genes associated with DYRK1A-mediated promotion of TGF-β/SMAD signalling, we generated a Venn diagram, which showed that there were 25 overlapping genes among those coexpressed with DYRK1A, SMAD2 and SMAD3 in liver cancer and DYRK1A-interacting proteins." (PMID 35655269, 2022). "VD could therefore be a strong candidate for liver cancer prevention in the context of aberrant Smad3 signaling." (PMID 27456065, 2016). "Moreover, SMAD3 has excellent potential as a gene therapeutic agent for liver cancer treatment." (PMID 34579396, 2021).
liver cancer (continued). "Conversely, in liver cancer cells, YAP promotes the cytoplasmic retention of Smad3, facilitating the development of tumor-initiating stem-like cells." (PMID 40673277, 2025). "Several studies have demonstrated that hesperidin exhibits protective effects against chemically induced liver cancer, potentially by inhibiting the TGF-β1/Smad3 signaling pathway." (PMID 41509136, 2025). "In studies of liver cancer metastasis, STAT3 was founded to be cooperated with Snail-Smad3/TGF-B1 signaling pathway, promoting cell migration." (PMID 37038114, 2023). "SMAD2 and SMAD3 correlated with autophagy-related scores (based on ATG12, ATG7, ATG3, ATG5, ATG4B, PIK3C3, PRKAA2, and GABARAPL1) in liver cancer." (PMID 37790613, 2023). "CHI3L1 can also regulate liver cancer potentially by regulating the TGF-β signaling pathways with activating kinase to phosphorylate SMAD2 and SMAD3." (PMID 34991559, 2022). "The results showed that SMAD3 had strong H3K27ac signals in eight common malignant tumor samples, while the NR5A1 only had H3K27ac signals in liver cancer samples." (PMID 34722892, 2021). "The proapoptotic effect of SMAD3 involves TGF-β signaling and activation, which selectively take place in liver cancer cells." (PMID 34579396, 2021). "Previous studies indicate that β2SP is a key TGF-β/Smad3/4 adaptor and transcriptional cofactor that can regulate TGF-β signaling and liver cancer development." (PMID 27248179, 2016). "β2-Spectrin (β2SP/SPTBN1, gene SPTBN1) is a key TGF-β/SMAD3/4 adaptor and transcriptional cofactor that regulates TGF-β signaling and can contribute to liver cancer development." (PMID 27248179, 2016). "Another study showed that different thresholds of Smad3 activation control TGF-β responses in hepatocytes and that liver cancer-derived HCV core protein, by decreasing Smad3 activation, switches TGF-β growth inhibitory effects to tumor-promoting responses." (PMID 21994721, 2010).
ovarian carcinoma (30 papers, 2009 to 2025). A malignant neoplasm originating from the surface ovarian epithelium. "We found that a low expression level of CDKN2B and WNT11 was associated with longer survival in ovarian cancer patients, while high expression levels of SMAD3, ZFYVE16, BMP6, LEFTY1, and DVL2 were significantly associated with poor survival." (PMID 38403634, 2024). "Taken together, the present findings of our study suggested that a double-negative, namely, positive, regulatory circuit among CASC15 and SMAD3 may underlie CASC15-mediated ovarian cancer cell EMT and metastasis induction." (PMID 35342355, 2022). "SMAD3 can promote ovarian follicle development, and mutation of this gene can cause ovarian cancer." (PMID 35052428, 2021). "Though CAAs can modulate ovarian cancer metastasis, studies also reported that ovarian cancer can induce CAA formation via activating the TGF-β1/SMAD3/TRIB3 pathway in reverse, which suppresses the phosphorylation of CEBPβ." (PMID 40709184, 2025). "We then transiently overexpressed Smad2 and Smad3 in ovarian cancer cells, CAOV3 and SKOV3, respectively, and found that only the overexpression of Smad2 increased the mRNA levels of USP9X." (PMID 40246814, 2025). "Here, we observed that in ovarian cancer spheroids, the Smad3 pathway was activated by TGFβ1 and upregulated the expression of Snail and N-cadherin, which are crucial genes in the EMT process." (PMID 34621667, 2021). "We evaluated the usefulness of YAP, TEAD4, SMAD2, SMAD3, H2A.X, ALD1A1, CD71, TKT and TKTL1 as diagnostic or prognostic markers in patients with ovarian cancer." (PMID 34205023, 2021). "SMYD3 and ITGB6 activated the TGFβ1/Smad3 pathway and then induced the upregulation of Snail, Vimentin and N-cadherin and the downregulation of E-cadherin in 3D-cultured ovarian cancer spheroids." (PMID 34621667, 2021). "In the present study, we confirmed that the blockade of UCHL5 activity by the DUB inhibitor bAP15 inhibited expression of phospho-Smad2/Smad3 in a concentration-dependent manner and induced apoptosis in ovarian cancer cells." (PMID 31666925, 2019). "In ovarian cancer, SMAD3 acts alone or in conjunction with SMAD4 to regulate transcription of EMT target genes." (PMID 28060758, 2017). "Here, we show that in mesenchymal-like ovarian cancer cells, 2ME2-mediated arrest in mitosis induced the phosphorylation of Smad3 and a reduction in Smad3 levels, prior to TGF-β addition." (PMID 22927969, 2012). "Mutations in BRCA1 are often seen in BRCA1-associated breast and ovarian cancers, indicating that genetic mutations in BRCA1 are linked to loss of function in Smad3-mediated TGF-β signaling." (PMID 19768112, 2009). "Previous research showed that PD169316 was a specific inhibitor of p38 MAPK by inhibiting the phosphorylation and nuclear translocation of SMAD2 and SMAD3 induced by TGFβ, and it has been well studied in human ovarian cancer cells and in equine digital vein endothelial cells." (PMID 37686221, 2023). "This study first described a miR-23b-3p/miR-24-3p-mediated positive feedback loop between CASC15 and SMAD3, which may reflect the underlying molecular mechanism of CASC15's oncogenic function in ovarian cancer." (PMID 35342355, 2022). "When ovarian cancer spheroids were treated with latent TGFβ1, the activation of the Smad3 pathway could also be inhibited if ITGB6 was blocked by a specific antibody." (PMID 34621667, 2021). "Higher phosphorylation levels of Smad3 were found in 3D-cultured HEY and A2780 cells than in 2D-cultured cells, which indicated that TGFβ1/Smad3 might play a role in promoting the EMT process in ovarian cancer spheroids." (PMID 34621667, 2021). "Since the TGFβ1/Smad3 signal transduction pathway is involved in inducing EMT in ovarian cancer, we aimed to identify whether the TGFβ1/Smad3 pathway is more activated in 3D-cultured ovarian cancer spheroids than in 2D-cultured ovarian cancer cells." (PMID 34621667, 2021).